EIF4G1 (eukaryotic translation initiation factor 4 gamma 1)
Diseases named in the same sentence as EIF4G1 in open-access papers (continued):
Sharing a sentence is not in itself a finding about the gene and the disease.
Parkinsonism (5 papers, 2012 to 2021). Characteristic neurologic anomaly resulting from degeneration of dopamine-generating cells in the substantia nigra, a region of the midbrain, characterized clinically by shaking, rigidity, slowness of movement and difficulty with walking and gait. "Mutations in seven genes were robustly associated with autosomal dominant (SNCA, LRRK2, EIF4G1, VPS35) or recessive (parkin/PARK2, PINK1, DJ1/PARK7) PD or parkinsonism." (PMID 29881367, 2018).
squamous cell lung carcinoma (5 papers, 2002 to 2023). A carcinoma arising from squamous bronchial epithelial cells. "In our study, we not only found the overexpression of EIF4G1 in NSCLC besides squamous cell lung carcinoma, but also found that EIF4G1 affects the mTOR signalling pathway in A549 cells." (PMID 33523588, 2021). "However, the effect of EIF4G1 on the prognosis, biological function and the relevant mechanism in lung squamous cell carcinoma (LSCC) is unclear." (PMID 36897548, 2023).
inflammatory breast carcinoma (4 papers, 2015 to 2021). An advanced, invasive breast adenocarcinoma characterized by the presence of distinct changes in the overlying skin. "Considering its crucial role in initiating cap-dependent translation, it has been reported that overexpression of eIF4G1 promotes both inflammatory breast cancer cell survival and the formation of tumor emboli." (PMID 27668427, 2016).
mesothelioma (4 papers, 2009 to 2020). A usually malignant and aggressive neoplasm of the mesothelium which is often associated with exposure to asbestos. "Their analysis revealed that patients with high EIF4G1 expression had lower median survival compared to the patients with low/medium expression (for mesothelioma, p = 0.0043)." (PMID 32659970, 2020). "Based on mRNA expression data for EIF4G1 from TCGA datasets, they analyzed the survival of patients with different cancer, including mesothelioma." (PMID 32659970, 2020).
ovarian carcinoma (4 papers, 2016 to 2023). A malignant neoplasm originating from the surface ovarian epithelium. "Associations of cancerous eIF4G1 expression with clinicopathologic characteristics of ovarian cancer." (PMID 27668427, 2016). "Ovarian cancer patients (n = 182 to n = 316) showed 24 to 37% of amplification and or up-regulation in EIF4G1." (PMID 31496918, 2019). "A correlation was observed between eIF4G1 cytoplasmic expression and the pathological parameters of 134 cases of ovarian cancer." (PMID 27668427, 2016). "Positively stained eIF4G1 was primarily located in the cytoplasm of ovarian cancer cells and manifested as light brown and brown particles." (PMID 27668427, 2016). "In summary, our results exhibited the first evidence that eIF4G1 overexpression correlates with the development of ovarian cancer." (PMID 27668427, 2016). "To investigate the influence of eIF4G1 on the prognosis of ovarian cancer patients, we generated survival curves and compared the progression-free survival times and overall survival times according to the expression of eIF4G1 based on protein level." (PMID 27668427, 2016). "In contrast to OSE, the expression of eIF4G1 was much higher in the ovarian cancer samples (P = 0.0007)." (PMID 27668427, 2016). "Using a series of fresh frozen human tissue specimens, we observed that eIF4G1 mRNA is up-regulated in ovarian cancer tissue compared to normal OSE specimens." (PMID 27668427, 2016). "To further investigate the possible correlations between eIF4G1 expression levels and the clinicopathological characteristics of patients, we followed 134 patients with ovarian cancer." (PMID 27668427, 2016). "The results demonstrated that ovarian cancer patients with high expression of eIF4G1 tended to have lower overall survival rates." (PMID 27668427, 2016). "Mechanistic studies remain to be undertaken to further unravel the role of eIF4G1 in ovarian cancer." (PMID 27668427, 2016). "Statistical analysis was conducted to determine the correlation of the eIF4G1 protein levels with the clinicopathological characteristics and prognosis in ovarian cancer." (PMID 27668427, 2016). "Analyzing the correlation between eIF4G1 expression and clinicopathological features, we observed that eIF4G1 expression in early stages of ovarian cancer according to FIGO staging is significantly lower than in advanced stages." (PMID 27668427, 2016). "Furthermore, we performed IHC to examine the dynamics of eIF4G1 expression of different characters based on complete follow-up data in those 134 ovarian cancer tissues and in normal ovarian epithelial cell specimens." (PMID 27668427, 2016). "The mRNA and protein expression levels of eIF4G1 in ovarian cancer tissues were remarkably higher than those in normal ovarian tissues, suggesting that the increased expression of eIF4G1 exists not only at the post-transcriptional level but also at the transcriptional level." (PMID 27668427, 2016). "Besides, we compared the eIF4G1 mRNA expression of ovarian cancer tissues and normal ovarian surface epithelial cells from the microarray data (GEO accession numbers GSE18521 and GSE40595)." (PMID 27668427, 2016). "In order to determine whether there is any relationship between the level of eIF4G1 expression and the prognosis in ovarian cancer patients, we performed Kaplan–Meier analysis and the log-rank test." (PMID 27668427, 2016). "Therefore, we propose to investigate the expression and clinicopathological significance of eIF4G1 in ovarian cancer patients." (PMID 27668427, 2016). "However, little is known regarding the characteristics of eIF4G1 expression and its clinical significance in ovarian cancer." (PMID 27668427, 2016). "Moreover, our results also indicate that eIF4G1 expression correlates with the presence of omentum metastasis, supporting that this protein acts as an oncogene in the progression of ovarian cancer." (PMID 27668427, 2016).
ovarian carcinoma (continued). "Thus, eIF4G1 may contribute to the occurrence and metastasis of ovarian cancer and can serve as a potential therapeutic target for the treatment of ovarian cancer." (PMID 27668427, 2016). "Thus, eIF4G1 can be a therapeutic target for ovarian cancer treatment." (PMID 27668427, 2016). "Thus, we hypothesized that altered expression of eIF4G1 plays a role in ovarian cancer." (PMID 27668427, 2016). "However, the relation between eIF4G1 and ovarian cancer remains unclear." (PMID 27668427, 2016). "In addition, we also analyzed two public ovarian cancer microarrays (GSE18521 and GSE40595) and the results demonstrated support that eIF4G1 is an oncogene." (PMID 27668427, 2016). "Our results demonstrated that the mean staining intensity of eIF4G1 in ovarian cancer tissues was significantly greater than the intensity in normal ovarian epithelial cell specimens, which is consistent with previous RT-PCR results." (PMID 27668427, 2016).
cervical carcinoma (3 papers, 2019 to 2024). A carcinoma arising from either the exocervical squamous epithelium or the endocervical glandular epithelium. "Cervical cancer patients (n = 190 to n = 275) showed a range of 33 to 36% amplification and or up-regulation in EIF4G1." (PMID 31496918, 2019). "from head and neck, pancreatic, lung, renal, breast, bladder, prostate, and cervical cancer and found a high level of EIF4G1 protein level in these cell lines." (PMID 31496918, 2019).
head and neck cancer (3 papers, 2019 to 2023). A primary or metastatic malignant neoplasm affecting the head and neck. "In head and neck cancer, the mutation of EIF4G1 affects the activation of mTOR signaling." (PMID 36897548, 2023). "Further, 28 to 33% of Head and Neck cancer patients (n = 279 to n = 496) showed amplification and or up-regulation in EIF4G1." (PMID 31496918, 2019).
oral squamous cell carcinoma (3 papers, 2022 to 2023). "The overexpression of METTL14 promoted autophagy by decreasing eukaryotic translation initiation factor 1 (eIF4G1) mRNA expression, thereby inhibiting the migration, invasion, and proliferation of oral squamous cell carcinoma (OSCC) cells." (PMID 36632456, 2023). "METTL14 directly binds to eIF4G1 mRNA and reduces the stability of eIF4G1 RNA by mediating m6A modification, thereby regulating autophagy levels and effectively reducing the growth of oral squamous cell carcinoma." (PMID 36360287, 2022). "FTO silencing can increase the methylation level of eIF4G1, and YTHDF2 can recognize the methylation site of eIF4G1, which leads to mRNA degradation and reduced eIF4G1 protein expression, thereby promoting autophagy and reducing the occurrence of oral squamous cell carcinoma (OSCC)." (PMID 34787056, 2022). "In oral squamous cell carcinoma, after FTO knockdown, YTHDF2 binds with eIF4G1 transcripts containing m6A, resulting in mRNA degradation and downregulating the expression of eIF4G1 protein, thereby activating autophagy and suppressing tumor growth." (PMID 36632456, 2023).
stomach cancer (3 papers, 2019 to 2024). "The distribution of mutations of 133 UPR related genes in stomach cancer were exhibited in waterfall plot, it is estimated that EIF4G1, DDX10, and EIF2AK3, which have the highest mutation rate, have a mutation rate of 4%, and the mutation type is predominantly missense mutations." (PMID 38700505, 2024). "Esophageal carcinoma and stomach cancer patients (n = 181 to n = 396) showed 12 to 30% of amplification and or up-regulation in EIF4G1." (PMID 31496918, 2019).
colorectal cancer (2 papers, 2018 to 2023). A primary or metastatic malignant neoplasm that affects the colon or rectum. "Concomitantly, EIF4G1 expression is associated with the PI3K-AKT pathway in colorectal cancer and it has been shown that SBI-756 blocks EIF4G1 function and inhibits AKT/mTORC1 signaling in melanoma cancers." (PMID 36897548, 2023).
endometrial cancer (2 papers, 2019). Primary or metastatic malignant neoplasm involving the endometrium (mucous membrane that lines the endometrial cavity). "With Endometrial cancer, 8 to 34% of patients (n = 56 to n = 232) showed amplification and or up-regulation in EIF4G1." (PMID 31496918, 2019). "However, percent amplification of EIF4G1 varies for other cancers from ~ 5% (Endometrial cancer), ~ 9% (non-small lung cancer) and ~ 4% (Esophagus cancer)." (PMID 31496918, 2019).
glioma (2 papers, 2019). A benign or malignant brain and spinal cord tumor that arises from glial cells (astrocytes, oligodendrocytes, ependymal cells). "In case of adrenal cancer, Brain lower grade glioma, colorectal, liver, and testicular cancer, patients showed a range of 5 to 10% amplification and or up-regulation in EIF4G1." (PMID 31496918, 2019). "These analyses reveal indeed that the expression of EIF4G1 and EIF4G2 is significantly increased in gliomas whereas EIF4G3 is decreased in gliomas and all GBM subtypes." (PMID 31795417, 2019). "Interestingly, our REMBRANDT analysis showed that both EIF4G1 and EIFG2 are overexpressed in gliomas." (PMID 31795417, 2019).
Pancreatic cancer (2 papers, 2019 to 2025). "Interestingly, 100% patients (n = 96) of QCMG dataset for Pancreatic cancer showed up-regulation in EIF4G1, another dataset for Pancreatic cancer patients showed a range of 7 to 9% of amplification and or up-regulation in EIF4G1." (PMID 31496918, 2019).
adenosquamous carcinoma (1 paper, 2021). A carcinoma composed of malignant glandular cells and malignant squamous cells. "Of the 128 cases of NSCLC, the mRNA expression of EIF4G1 in adenocarcinoma (75/128), squamous carcinoma (42/128), large cell carcinoma (4/128) and adenosquamous carcinoma (3/128) had no statistical difference, but its expression was higher in sarcomatoid carcinoma (4/128)." (PMID 33523588, 2021).
asthenozoospermia (1 paper, 2019). "A larger sample size should be investigated to further confirm the role of the EIF4G1 mutation in severe asthenospermia." (PMID 31268247, 2019). "Here, we found biallelic mutations in EIF4G1 from an infertile patient with severe asthenozoospermia and revealed that these mutations may be the key factor responsible for infertility due to this condition." (PMID 31268247, 2019). "Our present study identified biallelic mutations in the EIF4G1 gene of a patient with severe asthenozoospermia, in which the EIF4G1 protein level was significantly decreased, the spermatozoa had lost their motility and the spermatozoa showed a variety of morphological and ultrastructural defects." (PMID 31268247, 2019). "Hence, our study confirms that the EIF4G1 gene mutation may be a novel pathogeny of severe asthenozoospermia and provides more information about severe asthenozoospermia for researchers and clinicians." (PMID 31268247, 2019). "Our findings are the first to suggest that EIF4G1 may be a novel candidate gene that is relevant to severe asthenozoospermia." (PMID 31268247, 2019).
autism spectrum disorder (1 paper, 2025). A spectrum of developmental disorders that includes autism, and Asperger syndrome. "Proteomic analysis revealed that EIF4G1 was a potential target of Cullin 3 (CUL3) deficiency, a risk factor for autism spectrum disorder (ASD) and SCZ that caused cellular and behavioral defects." (PMID 40078531, 2025).
Bladder cancer (1 paper, 2019). "Our analysis revealed that 14% to 20% of Bladder cancer patients (n = 126 to n = 408) showed amplification and or up-regulation in EIF4G1 in different datasets." (PMID 31496918, 2019).
COVID-19 (1 paper, 2025). A disease caused by infection with severe acute respiratory syndrome coronavirus 2. "Five genes, including PAFAH2, LINC02915, CLSPN, EIF4G1 and IFI27, were predictors of both COVID-19 and RSV-LRTI hospitalization." (PMID 41279033, 2025).
developmental delay (1 paper, 2025). "Of note, the genetic variants of EIF4G1 and EIF3E have been linked to PD, while EIF4A2 has been described in pediatric cases with developmental delay and dystonia-tremor syndrome." (PMID 40194557, 2025).
ischemia (1 paper, 2022). A hypoperfusion of the BLOOD through an organ or tissue caused by a PATHOLOGIC CONSTRICTION or obstruction of its BLOOD VESSELS, or an absence of BLOOD CIRCULATION. "Prior to the study of the phosphorylation status of eIF4G1 under IR stress, we firstly analyzed the protein expression in brain samples from the ischemia model by Western blotting." (PMID 35163752, 2022). "In this report, we explore the hypothesis that phosphorylation of eIF4G1 can be a differential control mechanism between brain regions that are resistant and vulnerable to ischemia." (PMID 35163752, 2022).
kidney cancer (1 paper, 2019). Primary or metastatic malignant neoplasm involving the kidney. "In case of the patients (n = 65 to n = 3520) with kidney cancer showed 9 to 12% amplification and or up-regulation in EIF4G1." (PMID 31496918, 2019).
laryngeal squamous cell carcinoma (1 paper, 2024). A squamous cell carcinoma that arises from the larynx. "EIF4G1 is highly expressed in various types of tumors and affects the prognosis of patients with laryngeal squamous cell carcinoma (LSCC)." (PMID 38405671, 2024).
meningioma (1 paper, 2020). A generally slow growing tumor attached to the dura mater. "Inhibiting the activity of ILK affected the levels of key proteins known to be key players in meningioma pathobiology namely EIF4G1, CSNK2A1, and several others." (PMID 32974197, 2020).
prostate tumor (1 paper, 2018). "Further, our immunohistochemistry analysis of eIF4G1 protein in 30-week old TRAMP prostate tumor tissues and wild-type (WT) prostate tissue revealed that eIF4G1 protein level was significantly (p < 0.0001) elevated in TRAMP prostate tissue as compared to WT prostate tissue." (PMID 29748619, 2018). "Analysis of TMA showed that 65% tissues showed high eIF4G1 expression in grade 5 prostate tumor samples and 49% of the tissues have high eIF4G1 staining in grade 4 tumor samples while with grade 3 tumor sample eIF4G1 expression was more or less evenly distributed for low, moderate and high." (PMID 29748619, 2018). "Further our analysis of the eIF4G1 staining intensity based on tumor grade showed that normal prostate tissue has lowest staining intensity and with a graded increase in the tumor; staining intensity is increased statistically significant (normal prostate vs grade 3, 4, 5 prostate tumor p < 0.0001)." (PMID 29748619, 2018). "To test the function of eIF4G1, we first analyzed the eIF4G1 protein levels in different PCa cell lines (LNCaP, C4-2B, 22Rv1, DU145, PC3) and in TRAMP prostate tumor tissues." (PMID 29748619, 2018).
sarcomatoid carcinoma (1 paper, 2021). A malignant epithelial neoplasm characterized by the presence of spindle cells and anaplastic morphologic features. "In consistence, we herein found that high expression level of EIF4G1 is closely related with the poor differentiation in sarcomatoid carcinoma, suggesting EIF4G1 has potential to serve as a therapeutic target of pulmonary sarcomatoid carcinoma." (PMID 33523588, 2021).
Serous Ovarian Cancer (1 paper, 2016). "Immunohistochemistry (IHC) was used to examine the expression of eIF4G1 at the protein level in 134 patients with serous ovarian cancer and 18 normal ovarian tissues." (PMID 27668427, 2016). "The expression of eIF4G1 was upregulated in serous ovarian cancer tissues at both the mRNA (P = 0.0375) and the protein (P = 0.0007) levels." (PMID 27668427, 2016). "We examined 40 serous ovarian cancer specimens and 27 normal OSE specimens using quantitative RT-PCR for mRNA and analyzed the difference in the eIF4G1 mRNA expression between the tumor and the normal OSE specimens." (PMID 27668427, 2016).